MIP (major intrinsic protein of lens fiber)
Diseases named in the same sentence as MIP in open-access papers (continued):
Sharing a sentence is not in itself a finding about the gene and the disease.
tumor (17 papers, 2010 to 2024). "This is consistent with findings across multiple tumour sites associating MiP with aggressive disease and poorer patient outcomes." (PMID 37169775, 2023). "For tumors with homogeneous hyperdensity or hypodensity compared to the surrounding normal liver, MiP or MinIP projections should, respectively, reflect the tumor's trajectory across all time‐resolved datasets." (PMID 39284228, 2024). "The radiation induced enhanced uptake of the small molecule MIP-1145 is in line with previous reports attributing an improved delivery of nanomedicine such as liposomal doxorubicin to the irradiated tumor." (PMID 30042828, 2018). "There was also a significantly longer tumor doubling times for MIP/SP and MIP/SP-N saline-treated xenografts, in comparison to MIP/ZEO xenografts (p<0.005)." (PMID 22069448, 2011). "To overcome the low transduction efficiency of the plasmid expressing GFP-MIP and for inhibiting tumor cell growth, we prepared a synthetic MIP fused to Tat, a cell-permeable peptide (Tat-MIP)." (PMID 21423613, 2011). "Activation of SRC in tumor-associated macrophages is induced by tumor-derived cytokines and chemokines (e.g., TNF, MIP, SDF-1), which amplify the production of inflammatory cytokines (e.g., TNF, IL1β, IL6) to reciprocally activate SRC in a feed-forward loop and promote PDAC progression." (PMID 37120696, 2023). "Despite this, MIP is a candidate tumor suppressor, while BRCA1 and VHL are known tumor suppressors." (PMID 37742294, 2023). "At the same time, MiP can be stimulated for a long time, which may lead to atypical cell proliferation and eventually constitute a tumor." (PMID 36766625, 2023). "The tumor size in mice injected with the Au–MIP microgels was smaller than that in control mice, indicating that Au–MIP microgels might have applications as novel radiation sensitizers in antipancreatic cancer radiation therapy." (PMID 32806755, 2020). "This, together with previous in-vivo studies demonstrating greater tumor regression of xenografts of MIP/SP cells to chemotherapy led us to examine if tumor xenografts overexpressing the N-terminus domain of SPARC also had a heightened sensitivity to chemotherapy." (PMID 22069448, 2011). "Additionally, they can promote the release of inflammatory factors such as TNF-α, MIP, and MCP and participate in the formation of an anti-tumor inflammatory microenvironment." (PMID 33363026, 2020). "Inspite of the production of these MIP proteins, the immune response to the tumours is not effective probably due to functional defects in the effector cells." (PMID 21092330, 2010).
cancer (5 papers, 2018 to 2022). A tumor composed of atypical neoplastic, often pleomorphic cells that invade other tissues. "In patients with polyps, ACKR2 markedly correlated solely with CCL3, which was also the strongest correlation in CRC patients, although in cancer the significant correlations were present between the receptor and all examined chemokines from MIP and MCP family." (PMID 33374792, 2020).
bacterial infection (1 paper, 2011). "It has been reported in these studies that the neutrophil chemoattractant KC is essential for recruiting neutrophils and regulating other chemokines such as MIP and LIX (lipopolysaccharide-induced CXC chemokine) to provide innate immune responses against bacterial infection from the lungs in mice." (PMID 21943386, 2011).
MIP also shares sentences with these, for which no sentence is quoted: gastric cancer (3 papers); nuclear cataract (3); autosomal dominant cataracts (2); Glucose intolerance (2); lamellar cataracts (2); ovarian carcinoma (2); adenocarcinoma (1); Age-related cataract (1); Alzheimer disease (1); Anterior polar cataract (1); cardiovascular disease (1); chronic obstructive pulmonary disease (1); colon carcinoma (1); cystic kidney disease (1); depression (1); endometrioid ovarian cancer (1); extrapulmonary tuberculosis (1); hemoglobinopathies (1); hemorrhage (1); IgA nephropathy (1); kidney cancer (1); lung diseases (1); macular degeneration (1); Miscarriage (1); multiple sclerosis (1); nephrogenic diabetes insipidus (1); neuroblastoma (1); neurodegenerative disease (1); non-small cell lung carcinoma (1); Palmoplantar keratoderma (1).
A further 9 diseases each share a sentence with MIP in 1 paper.